INS (insulin)
Diseases named in the same sentence as INS in open-access papers (continued):
Sharing a sentence is not in itself a finding about the gene and the disease.
cognitive decline (continued). "Intranasal insulin has emerged as a promising potential treatment for cognitive decline." (PMID 40980544, 2025). "To investigate how impaired glucose metabolism affects AD cognitive decline, we examined reduced insulin production due to STZ-induced pancreatic β-cell loss, and chronic exposure to HFHS diet to induce insulin resistance." (PMID 40964391, 2025). "Preclinical and clinical studies have highlighted mitochondrial impairment, enhanced oxidative stress, disrupted insulin signaling in the central nervous system, and impaired synaptic plasticity as key elements linking metabolic dysregulation to cognitive decline." (PMID 41157142, 2025). "The effects of low estrogen levels on insulin signaling do not solely affect T2D and cardiovascular disease risk but have been associated with increased cognitive decline as well." (PMID 41294899, 2025). "Furthermore, inflammatory cytokines have been shown to interfere with insulin function at the cellular level and worsen its neurotoxic effects, thus exacerbating cognitive decline." (PMID 39286235, 2024). "Future research is needed to confirm our findings and investigate whether normalizing brain insulin signaling along the AKT1 pathway can slow down the late-life cognitive decline and the development of AD." (PMID 38029396, 2024). "Additionally, low insulin levels impair the brain’s ability to clear Aβ, exacerbating synaptic dysfunction and cognitive decline." (PMID 39766390, 2024). "Since cognitive decline close to death is non-linear, we examined the association between brain insulin signaling measures and the decline in global cognition using the sigmoidal mixed-effects model." (PMID 38029396, 2024). "Another possible factor that may contribute to these findings is that the intervention was associated with higher glucose levels, which are known to contribute to cognitive decline via central insulin sensitivity." (PMID 37315924, 2023). "Insulin signaling affects amyloid precursor protein (APP) processing, favoring the non-amyloidogenic pathway in proper signaling, while disruptions shift it toward the amyloidogenic pathway, increasing Aβ production linked to cognitive decline." (PMID 38002034, 2023). "Importantly, interventions that improve metabolic function, such as caloric restriction or drugs that target insulin or mTOR signaling, delay the onset of aging-related cognitive decline." (PMID 35406051, 2022). "Thus, an alteration to insulin signaling can lead to metabolic impairment, cognitive decline, and even the onset and development of AD." (PMID 35457168, 2022). "This could mean that in the disease state with impaired insulin signaling in the brain, where tau hyperphosphorylation occurs, the aggregated tau could further contribute to insulin signaling dysfunction, resulting in cognitive decline." (PMID 34725612, 2021). "Studies in brain tissue from animal models of neurodegeneration show that APN and APN receptors impact signaling and neuronal function in the brain, including neuronal insulin resistance, synaptic plasticity, excitotoxicity, neurodegeneration and cognitive decline." (PMID 34279477, 2021). "Longitudinal studies with long follow-up will define whether the increased insulin-stimulated BGU in the context of IR precedes cognitive decline, and/or further aggravation of the metabolic status." (PMID 33917464, 2021). "Similarly, insulin users experienced an accelerated cognitive decline compared to DPP-4i users (−1.00, −1.95; −0.04) when weighted for dropout." (PMID 34857046, 2021). "Thus, under physiological conditions, insulin acts as a protective factor for brain function and contributes to the prevention of cognitive decline." (PMID 34439505, 2021). "First, AD could be a partial consequence of insulin resistance, which affects insulin signalling and favours in the brain abnormal deposition of β-amyloid peptide (Aβ) and phosphorylated tau (pTau) accumulation, leading in turn to cognitive decline." (PMID 32290868, 2020).
cognitive decline (continued). "First, AD could be a partial consequence of insulin resistance, which affects insulin signaling and favors abnormal deposition of Aβ and phosphorylated Tau accumulation in the brain, leading to cognitive decline." (PMID 33328854, 2020). "Even in the absence of T2DM, there is a risk of cognitive decline with decreasing insulin sensitivity in elderly individuals." (PMID 31878021, 2019). "This raises the question of whether insulin-sensitizer drugs could be useful in preventing or arresting cognitive decline." (PMID 31835729, 2019). "In addition, brain iron overload leads to insulin resistance and subsequently cognitive decline in obesity animal and human models." (PMID 30043289, 2018). "Consequently, insulin resistance and impaired insulin signaling are significantly related to tau hyperphosphorylation and Aβ deposition in AD, and ultimately contribute to cognitive decline." (PMID 28764741, 2017). "Glucose/energy hypometabolism in the brain might be a consequence of an insulin resistant brain state, which seems to be involved in cognitive decline, as suggested in particular in AD and its animal models." (PMID 26110057, 2015). "Considering the predominant role of p110α in insulin signaling, selective manipulation of p110α activity may be beneficial to treat epilepsy or ameliorate cognitive decline in AD." (PMID 24592210, 2014). "p110α – insulin signaling to epilepsy and cognitive decline?" (PMID 24592210, 2014). "The cognitive decline is involved in brain insulin dysfunction." (PMID 24481061, 2014). "Fat induced cognitive decline is probably mediated by increased insulin resistance." (PMID 23855966, 2013). "Reduced insulin signalling and DR both alleviated cognitive decline, but in subtly different ways." (PMID 21078113, 2011). "On one hand, Aβ was shown to impair insulin-PI3K-AKT signaling and insulin treatment was reported to improve cognitive function in patients with early AD, while on the other hand, AD transgenic mice with reduced insulin signaling were reported to be protected against cognitive decline." (PMID 20862226, 2010). "Additionally, pioglitazone, another insulin-sensitizing drug that exerts its glucose-lowering effects through the activation of peroxisome proliferator-activated receptors, has also been reported to ameliorate cognitive decline." (PMID 40979705, 2025). "Small pilot studies have indicated that intranasal insulin administration is a feasible treatment modality that can enhance cognitive functions, including delayed verbal memory and attention, offering a potential approach for addressing neurodegenerative disorders and cognitive decline." (PMID 40979705, 2025). "However, insulin intake demonstrates a connection with cognitive decline." (PMID 40818936, 2025). "Furthermore, as the duration of T2DM increases, the sustained decrease in BDNF and insulin levels may lead to structural changes in the brain, thereby accelerating cognitive decline in patients." (PMID 40933306, 2025). "Thus, a high-fat diet promotes brain insulin resistance and cognitive decline." (PMID 41294899, 2025). "Furthermore, central insulin resistance disrupts mitochondrial function, leading to increased oxidative stress and bioenergetic deficits that compromise neuronal health and synaptic function, creating a vulnerable environment for cognitive decline." (PMID 41341139, 2025). "Insulin is not only crucial for metabolic processes but also plays a significant role in learning and memory, showing that its dysregulation could contribute to cognitive decline." (PMID 39246604, 2024). "Treatment with FGF21 in HFD rats improved peripheral insulin sensitivity, hippocampal synaptic plasticity, increased dendritic spine density, restoration of brain mitochondrial function, and reduced apoptosis in brain cells, collectively mitigating cognitive decline." (PMID 39897964, 2024).
cognitive decline (continued). "Additionally, antidiabetic drugs such as metformin have been observed to improve insulin sensitivity and reduce inflammation in the brain, suggesting that they could slow or reverse the process of cognitive decline in patients with AD." (PMID 37332343, 2023). "In addition, insulin therapy has been shown to improve memory in patients with cognitive decline." (PMID 37095621, 2023). "Furthermore, the exogenous Cystatin C induces impairment of insulin signaling in hippocampal neurons, which could promote cognitive decline and AD development." (PMID 37342358, 2023). "Consequently, abnormalities in insulin function may precipitate neurodegeneration or cognitive decline." (PMID 37904099, 2023). "Additionally, we have not yet studied if these effects now herein documented are specific to hepatocytes or if they occur in other IDE-containing tissues, such as brain, where reduced insulin action is well-described from epidemiological studies to be a feature of cognitive decline with age." (PMID 35017319, 2022). "However, there is also evidence that dysregulation of insulin signaling in the mammalian CNS may contribute to age- and disease-related cognitive decline." (PMID 35798912, 2022). "Additionally, in AD, the impaired brain insulin signaling may contribute to cognitive decline via impaired hippocampal neuroplasticity, increased tau protein concentration, neuroinflammation and mitochondrial dysfunction." (PMID 34108878, 2021). "The higher plasma insulin and lower CSF insulin found in AD patients compared to healthy adults support the hypothesis that a decreased insulin transport into the brain may trigger cognitive decline and neurodegeneration." (PMID 34439505, 2021). "An impaired insulin signaling in the brain also changed integrin-linked kinase glycogen synthase kinase (GSK) 3β signaling and reduced the trafficking and function of postsynaptic glutamate receptors, thereby impairing synaptic plasticity and contributing to cognitive decline." (PMID 34108878, 2021). "Currently, there have been no particular treatments with established efficacy in counteracting cognitive decline or AD, so the implications of identifying AD as a disorder with an etiology rooted in faulty insulin signaling and irregular energy pathways could be critical in disease management." (PMID 32365816, 2020). "As synaptic strength in the hippocampus is thought to be essential for the formation of spatial learning and memory, this indicates the dysfunction of neuronal insulin signaling may play a critical role in hippocampal synaptic plasticity impairment and cognitive decline." (PMID 32471175, 2020). "Thus, modification of the insulin signaling pathway may be a promising strategy for preventing cognitive decline of patients with type II DM, MCI, and even AD." (PMID 27058526, 2016). "Furthermore, in another cohort of non-demented older adults, higher insulin levels (fasted insulin and AUCinsulin) and impairments in insulin sensitivity were found to be associated with increased rate of cognitive decline." (PMID 26074813, 2015). "There is also significant evidence that insulin and IGF signaling promote the aging process in many animals, raising the intriguing possibility that age-related cognitive decline may be mediated by the effects of insulin and IGFs on transcription factors and synapse function." (PMID 24672476, 2014). "Hence, ASK1 serves as a key factor in modulating insulin signal transduction, and its regulation might enhance cognitive decline in AD." (PMID 24481061, 2014). "Thus, regulation of adiponectin is important impaired insulin signal transduction to improve and also adiponectin may contribute to the improvement of cognitive decline in dementia." (PMID 24860814, 2014).
cognitive decline (continued). "Additionally, at the molecular level, insulin signaling pathway abnormalities affect neuronal energy metabolism, inducing mitochondrial dysfunction that exacerbates oxidative stress injury, reduces cerebrovascular reactivity, and impacts neuronal synaptic plasticity, accelerating cognitive decline." (PMID 40474525, 2025). "Thus, unbalanced insulin signaling, and metabolism may lead to cognitive decline and AD." (PMID 36895036, 2023). "In addition, incretin glucagon-like peptide 1 and the glucose-dependent insulinotropic polypeptide (GLP-1/GIP) receptor agonist could alleviate the cognitive decline in AD mice by activating the insulin signaling pathways to maintain the glucose metabolism of astrocytes." (PMID 35457168, 2022). "Before sacrifice, body weight, intraperitoneal glucose and insulin tolerance test (IP-ITT) were performed to evaluate peripheral parameters and also behavioral tests to determine cognitive decline." (PMID 34294142, 2021). "Based on this, it is of great interest to investigate the mechanism of restoration of the insulin signal in the brain as an action of ADPN, because it is useful for testing a possible pharmacological treatment for the improvement of cognitive decline." (PMID 32188008, 2020). "We assessed their cognitive decline using the Unified Huntington’s Disease Rating Scale, and their IGF-1 and insulin plasmatic levels, at baseline and once a year during the follow-up." (PMID 27627435, 2016). "Preclinical and clinical studies have reported positive results regarding the use of intranasal insulin in cognitive decline, notably AD, although not conclusive yet." (PMID 37511207, 2023). "This is particularly interesting given the large body of literature that demonstrates the negative effects of T2D on brain insulin resistance, oxidative stress, and cognitive decline." (PMID 36642814, 2023). "Our findings raise the possibility that insulin-induced increases in IFN-γ concentrations in the CNS may provide neuroprotection and attenuate cognitive decline." (PMID 35079029, 2022). "In addition to insulin, IGF-I, which is the most abundant member of the IGF family in the CNS, appears to influence cognitive decline in pathologic conditions." (PMID 23211425, 2012). "Preclinical evidence further supports these findings: in insulin-resistant rat models, DPP-4is such as sitagliptin and vildagliptin improve cognitive behaviors and restore cerebral mitochondrial function, demonstrating protective effects against diet-induced cognitive decline." (PMID 40831951, 2025). "Cognitive decline is reduced in metformin users when compared with non-users, whereas insulin and SU users may have larger point-wise decrements when compared with DPP4i users." (PMID 41146261, 2025). "Disrupted insulin and insulin-like growth factor (IGF) signaling within the brain impairs glucose metabolism, promotes amyloid-beta accumulation, and contributes to progressive neurodegeneration — features characteristic of both metabolic and cognitive decline." (PMID 41003796, 2025). "This work has some limitations: body fat and other parameters (e.g., insulin, testosterone, oestrogen levels), which may also play an important role on leptin, adiponectin and cognitive decline, were not collected." (PMID 38686200, 2024). "Indeed, accumulating research suggests that cognitive decline and the development of AD pathology is often preceded by brain insulin resistance, as revealed by diminished or even absent brain response to insulin." (PMID 39656485, 2024). "However, different biological mechanisms including insulin resistance, developmental disturbances, altered membrane functioning, and altered vascularization have been involved in HFD-induced neuronal damage and cognitive decline." (PMID 36834882, 2023). "The most recent clinical trial involving intranasal insulin reported no slowing of cognitive decline; however, several factors may have impacted the trial outcomes." (PMID 36555450, 2022).
cognitive decline (continued). "However, in line with findings of recent meta-analyses, insulin-treated participants showed larger cognitive decline than those not treated with insulin." (PMID 34777250, 2021). "Another limitation of the intranasal insulin literature is a relative lack of data from middle-aged individuals (for example, those aged 50 to 60) who may be at the earliest stages of measurable cognitive decline and AD-related neurobiological processes." (PMID 40980544, 2025). "Thus, we could not exclude the possibility that the cognitive decline observed in GK rats or exaggeration of cognitive dysfunction induced by sevoflurane were partly due to reduced insulin levels or increased insulin resistance in the brain." (PMID 29238302, 2017).